XRCC4 (X-ray repair cross complementing 4)
Diseases named in the same sentence as XRCC4 in open-access papers (continued):
Sharing a sentence is not in itself a finding about the gene and the disease.
colon cancer (3 papers, 2020 to 2026). "For this, we compared the XRCC4 protein and cellular O-GlcNAcylation levels between normal colon and colon tumor tissues using a mouse model of colitis-associated colon cancer." (PMID 41513635, 2026). "We confirmed that XRCC4 and O-GlcNAc levels were higher in colon tumor tissues than in normal colon tissues." (PMID 41513635, 2026). "Our previous interactome study showed an interaction between XRCC4 and OGT, implying that XRCC4 undergoes O-GlcNAc modifications in HCT116 colon cancer cells." (PMID 41513635, 2026). "Although the role of XRCC4 in V(D)J recombination is established mainly in rodent cells, a recent study showed that human XRCC4-knockout cell, generated from colon cancer HCT116 cell, was defective in V(D)J recombination." (PMID 33842963, 2021). "To determine the expression pattern of core NHEJ genes in colon cancer, we performed Oncomine analysis for XRCC6 (Ku70), XRCC5 (Ku80), PRKDC (DNA-PKcs), XRCC4 (XRCC4), LIG4 (DNA ligase 4), NHEJ1 (XLF), and PAXX (PAXX/XLS)." (PMID 33195430, 2020). "Similarly, elevated cellular O-GlcNAcylation and XRCC4 protein levels were observed in several colon cancer cell lines (HCT116, DLD1, and HT29) compared to non-cancer cell lines (CCD-33Co and CCD-112CoN)." (PMID 41513635, 2026).
leukemia (3 papers, 2015 to 2022). A malignant (clonal) hematologic disorder, involving hematopoietic stem cells and characterized by the presence of primitive or atypical myeloid or lymphoid cells in the bone marrow and the blood. "However, it was noticed that XRCC1 polymorphisms play an important role in the development of ALL, and postnatal exposure to x-rays can modulate leukaemia risk in the presence of APEX1, MLH1, and XRCC4 gene variants." (PMID 26045716, 2015).
pancreatic cancer (3 papers, 2017 to 2023). "The circBIRC6/XRCC4 axis highlighted in our findings paves the way for a potentially novel therapeutic approach to conquer platinum resistance in pancreatic cancer." (PMID 38012734, 2023). "Since pancreatic cancer has only low competence in homologous recombination (HR) repair we quantified the protein levels of Ku 70, Ku 80 and XRCC4." (PMID 28700650, 2017). "Additionally, our clinical findings underscore the predictive potential of the circBIRC6/XRCC4 axis for assessing platinum resistance in pancreatic cancer patients." (PMID 38012734, 2023). "Importantly, this suggests that the nuclear translocation of XRCC4 in pancreatic cancer cells largely depends on K115." (PMID 38012734, 2023). "Given the vital role of XRCC4 in DNA repair and chemoresistance, understanding the significance of its SUMOylation could have profound implications in overcoming therapeutic resistance in pancreatic cancer." (PMID 38012734, 2023). "This resistance is driven by SUMOylation-mediated XRCC4 nuclear translocation, amplifying the NHEJ repair process in DNA-damaged pancreatic cancer cells." (PMID 38012734, 2023). "CircBIRC6 encapsulated in CAF-derived EVs promoted XRCC4 nuclear localization via SUMOylation, consequently enhancing NHEJ repair efficiency in DNA-damaged pancreatic cancer cells, leading to platinum resistance." (PMID 38012734, 2023).
prostate carcinoma (3 papers, 2007 to 2023). A carcinoma that arises from epithelial cells of the prostate gland. "A case–control study carried out among 134 prostate cancer and 134 age-matched healthy controls reported XRCC4 single nucleotide polymorphisms (SNP) increases the risk of susceptibility to prostate cancer." (PMID 36765282, 2023).
retinoblastoma (3 papers, 2018 to 2023). A malignant tumor that originates in the nuclear layer of the retina. "Apart from one sample (#723), high levels of XRCC4 in human retinoblastoma moderately correlated with lower levels of apoptosis markers." (PMID 29415984, 2018). "The XRCC4 downregulation upon UHRF1 knockdown was observed in other retinoblastoma cell lines (Weri-Rb1 and SO-Rb50) and 293T cells, and occurred at the transcript level." (PMID 29415984, 2018). "In this regard, we examined nuclear factors involved in the repair of etoposide-induced DSBs, and identified XRCC4 as a key mediator regulated by UHRF1 in retinoblastoma cells." (PMID 29415984, 2018). "To compare the expression patterns of UHRF1 and XRCC4, we used two serial retinoblastoma sections for UHRF1 and XRCC4 immunostaining." (PMID 29415984, 2018). "Downregulation of XRCC4 by UHRF1 depletion sensitized retinoblastoma cells to more chemotherapy." (PMID 32258128, 2020). "Conversely, overexpression of UHRF1 increased the XRCC4 expression and stable knockdown of XRCC4 sensitized retinoblastoma cells to etoposide treatment, suggesting that XRCC4 is a key mediator for the drug sensitivity upon UHRF1 depletion in retinoblastoma cells." (PMID 29415984, 2018). "However, the XRCC4 expression in human retinoblastoma was much higher than that of normal retina." (PMID 29415984, 2018). "As in retinoblastoma cells, UHRF1 knockdown in 293T cells induced more intense apoptosis upon etoposide treatment, and overexpression of XRCC4 in UHRF1-depleted cells attenuated the apoptosis." (PMID 29415984, 2018). "We found that UHRF1-depleted retinoblastoma cells can recognize DNA damages normally but have markedly low expression of XRCC4 (X-ray repair cross complementing 4) among the components of nonhomologous end-joining (NHEJ) repair complex." (PMID 29415984, 2018). "Of note, XRCC4 expression is detectable in human normal retina unlike the case of UHRF1, and our data suggest that high UHRF1 expression during retinoblastoma tumorigenesis may further augment the XRCC4 expression in tumors." (PMID 29415984, 2018).
thyroid cancer (3 papers, 2024 to 2025). "In DNA repair-related studies on thyroid cancer, XRCC4 polymorphisms were analyzed in Portuguese, Chinese, and Arab populations." (PMID 38892180, 2024). "A study of a Chinese ethnic population evaluated the association of SNPs in the 3′-UTR double-strand break repair genes RAD51, RAD51B, BRCA1 (rs12516, rs8176318), BRCA2 (rs15869), XRCC4, and XRCC5 with the risk of thyroid cancer in 206 patients with PTC." (PMID 40361383, 2025). "scRNA-seq analysis showed reduced expression of the LIG4 gene at the mRNA level in normal follicular thyroid cells and thyroid cancer cells, but its activity is tightly regulated at the protein level by XRCC4 and DNA-PKcs." (PMID 38380364, 2024).
bladder transitional cell carcinoma (2 papers, 2017 to 2023). The most common morphologic subtype of urinary bladder carcinoma (over 90% of cases). "Rama et.al found XRCC4 genotype was associated with urothelial bladder cancer risk." (PMID 36765282, 2023).
endometrial cancer (2 papers, 2023 to 2024). Primary or metastatic malignant neoplasm involving the endometrium (mucous membrane that lines the endometrial cavity). "In conclusion, this study unveils a novel mechanism by which SMYD3 contributes to endometrial cancer, shedding light on its dynamic regulation of the LIG4/XRCC4/XLF complex in the NHEJ pathway." (PMID 38191478, 2024). "According to the analysis result, the highest frequency of XRCC4 alteration appeared for pan-cancer patients with adrenocortical carcinoma (ACC), endometrial cancer, ovarian and melanoma (> 2%) using the cBioPortal database." (PMID 36765282, 2023).
endometrioid ovarian carcinomas (2 papers, 2021). "Previous studies have shown that overexpression of the XRCC4 gene was dramatically linked to worse PFS and OS for patients with serous ovarian carcinoma, suggesting the prognostic significance of XRCC4 in serous and endometrioid ovarian carcinomas patients." (PMID 35052761, 2021). "Nevertheless, the high XRCC4 expression was correlated with a favorable OS in endometrioid ovarian carcinomas, which may be attributed to the less number of cases of endometrioid ovarian carcinomas in the database." (PMID 34539898, 2021).
endometriosis (2 papers, 2023 to 2025). The growth of functional endometrial tissue in anatomic sites outside the uterine body. "Through this analysis, we identified 42 genome-wide significant (5 × 10−8) genetic variants significantly associated with endometriosis, 6 of which were not reported previously: ABHD1/2p23.3, TMEM131/2q11.2, XRCC4/5q14.2, PPP1R9A/7q21.3, XKR6/8p23.1, and TRPS1/8p23.3." (PMID 40262193, 2025).
lymph node metastasis (2 papers, 2020 to 2023). "A risk model based on XRCC4, XRCC5 and XRCC6 showed that the risk score was related to the prognosis, gender, clinical stage, T stage, lymph node metastasis and metastasis of LUAD patients and was an independent risk factor for the prognosis of LUAD patients." (PMID 37737707, 2023).
melanoma (2 papers, 2016 to 2023). A malignant, usually aggressive tumor composed of atypical, neoplastic melanocytes. "In summary, PARP1 inhibitor seems to offer additional treatment opportunity to pre-selected melanomas displaying LIG4 (and/or XRCC4) deficiency." (PMID 27705909, 2016).
metabolic syndrome (2 papers, 2015 to 2023). A cluster of metabolic risk factors for CARDIOVASCULAR DISEASES and TYPE 2 DIABETES MELLITUS. "While this paper was under reviewing, two publications have reported patients with proven mutations in XRCC4, associated with primordial dwarfism or early-onset metabolic syndrome." (PMID 25872942, 2015). "The deficiency of XRCC4 could also associate with short stature, gonadal failure and early-onset metabolic syndrome." (PMID 36765282, 2023).
neuroblastoma (2 papers, 2015 to 2022). Neuroblastoma (NB) is the most common solid, extracranial childhood tumor. "Although the exact mechanism is not known, expression of TrkA tyrosine kinases accelerates IR induced DNA DSB repair by upregulating the expression of the NHEJ protein XRCC4 in neuroblastoma cell lines." (PMID 26546517, 2015). "Additionally, in human neuroblastoma cells, expression of XRCC4, a central component of NHEJ, was significantly upregulated upon overexpression of TrkA receptor tyrosine kinase leading to increased NHEJ activity." (PMID 26546517, 2015). "Consistently, along with Ku70 and Ku80, other key components of the NHEJ complex, namely DNA ligase 4 and XRCC4, were recovered with MILIP in neuroblastoma cells." (PMID 36445966, 2022).
primordial dwarfism (2 papers, 2015 to 2016). "Based on this observation in mice, human XRCC4 mutations associated with primordial dwarfism have been deemed as hypomorphic alleles." (PMID 25872942, 2015). "In contrast with embryonic lethality of the Xrcc4 KO mouse, nonsense mutations in human XRCC4 have recently been associated with primordial dwarfism and, in our cases, with adult-onset neurological impairment, suggesting an important role for DNA repair in the brain." (PMID 25872942, 2015). "A homozygous missense variant in XRCC4 was recently identified in a Saudi patient with primordial dwarfism, but it was not possible to establish its causative role because of the absence of any experimental validation." (PMID 25872942, 2015).
schizophrenia (2 papers, 2010 to 2024). A major psychotic disorder characterized by abnormalities in the perception or expression of reality. "Moreover, data from recent reports have revealed schizophrenia susceptibility loci on chromosome 5q14, which is in the vicinity of the XRCC4 gene." (PMID 20920336, 2010). "Using a similar research strategy, we found that polymorphisms of XRCC4 may confer genetically reduced susceptibility to CRC among Chinese schizophrenia patients." (PMID 20920336, 2010). "Thus, XRCC4 might be a potential candidate gene for the hypothesis that schizophrenia offers reduced susceptibility to malignancy." (PMID 20920336, 2010). "In the present study, our data based on Han Chinese samples provide further support for the assumption that XRCC4 might be involved in a potential protective mechanism against cancer in schizophrenia patients." (PMID 20920336, 2010).
serous ovarian carcinoma (2 papers, 2021). "Then, for XRCC4, overexpression of these genes was dramatically linked to worse PFS and OS for patients with serous ovarian carcinoma, HR=1.25 (1.07-1.46), P=0.004, HR=1.49 (1.27-1.74), P=0.0000." (PMID 34539898, 2021).
alcoholism (1 paper, 2022). "In support of this, a set of histones genes were identified in the protein–protein interaction studies, and these genes are also part of the alcoholism pathway that is highly enriched in the XRCC4 knockout cells treated with mirin." (PMID 35054780, 2022). "One theme that emerged was that blocking NHEJ pathways by either XRCC4 knockout or mirin treatment alone or in combination lead to pathways such as transcriptional mis-regulation in cancer, alcoholism, defense response to viruses, and response to oxygen levels." (PMID 35054780, 2022).
asthma (1 paper, 2018). "We saw an increase in expression of 3 DDRFs including Rad51 (Rheumatoid arthritis), XRCC4 (lesional skin), and BRCA2 (asthma) while 1DDRFs was downregulated." (PMID 29867559, 2018).
cervical cancer (1 paper, 2024). A primary or metastatic malignant neoplasm involving the cervix. "The same group confirmed in a later work that low XRCC4 expression was associated with better prognosis in cervical cancer patients treated with chemoradiotherapy (CRT)." (PMID 39199577, 2024).
cryptorchidism (1 paper, 2015). The failure of one or both testes of a male fetus to descend from the abdomen into the scrotum during the late part of pregnancy. "They presented also cryptorchidism, suggestive of gonadal failure, which has been found in other XRCC4-mutant patients." (PMID 25872942, 2015).
cutaneous melanoma (1 paper, 2016). A primary melanoma arising from atypical melanocytes in the skin. "Although downregulation/mutation of LIG4 (and its partner XRCC4) was detected only in approximately 7% of cutaneous melanomas in TCGA database, inhibition/inactivating mutation of other members of D-NHEJ potentially impairing DSB repair activity by the pathway were detected, too." (PMID 27705909, 2016).
dermatofibrosarcoma (1 paper, 2025). "So, four types of tumor have been now reported in patients with XRCC4-related MPD, namely dermatofibrosarcoma, mandibular osteoid osteoma, thalamic glioma, and jejunal gastrointestinal stromal tumor (GIST), respectively at 5, 20, 19 and 30-years-old." (PMID 40114033, 2025).
diabetes (1 paper, 2018). "Furthermore, other gene products related to DNA damage repair have been implicated in diabetes, most recently XRCC4." (PMID 29392078, 2018).
emphysema (1 paper, 2019). "We found a similar correlation for DNA ligase IV and XRCC4 expression and their low expression in emphysema." (PMID 30696938, 2019). "Next, we wanted to determine 53BP1, DNA ligase IV, XRCC4 and XLF expression, which form a complex to ligate the broken ends during the NHEJ process, in freshly isolated ATII cells from non-smokers, smokers and patients with emphysema." (PMID 30696938, 2019).
HIV-1 infection (1 paper, 2022). The type species of lentivirus and the etiologic agent of acquired immunodeficiency syndrome (AIDS). "The GMDR method was used to study the association of 10 SNPs in XRCC6 and XRCC4 genes with high-order interactions on HIV-1 infection." (PMID 36312587, 2022). "In gene-gene interaction analysis, significant SNP-SNP interactions of XRCC6 and XRCC4 genetic variations were found to play a potential role in the risk of HIV-1 infection." (PMID 36312587, 2022). "Positive associations were observed between XRCC6 rs132770 and XRCC4 rs1056503 genotypes and the susceptibility to HIV-1 infection." (PMID 36312587, 2022). "In addition, the genotype TT of XRCC4 rs1056503 showed significant association with increased susceptibility of HIV-1 infection in the codominant model (TT vs. GG, P = 0.035, OR = 1.698, 95% CI: 1.037-2.779) and recessive model (TT vs. TG+GG, P = 0.028, OR = 1.707, 95% CI: 1.060-2.750)." (PMID 36312587, 2022). "In this study, we conducted a case-control study in the northern Han Chinese population to investigate associations of 22 SNPs in XRCC7, XRCC6, XRCC5, XRCC4, and LIG4 genes with the risk of HIV-1 infection and the progression of AIDS." (PMID 36312587, 2022). "In addition, in the analysis of SNP-SNP interaction, our results provide evidence for a four-locus interaction between XRCC6 and XRCC4 variants in the risk of HIV-1 infection and further highlight the role of multilocus effects in the genetic component of HIV-1 infection." (PMID 36312587, 2022).
liver cirrhosis (1 paper, 2017). "XRCC4 expression was significantly correlated with pathological features including tumor stage, liver cirrhosis, and micro-vessel density." (PMID 29152133, 2017).
Majewski syndrome (1 paper, 2025). "Endocrine dysfunction, well reported in XRCC4-related MPD, is also observed in other DNA repair defects, including DNA2, BLM, NSMCE2-related MPD [MIM#615807, MIM#210900, MIM#617253], but also in other MPD such as Majewski syndrome." (PMID 40114033, 2025).
myeloma (1 paper, 2022). "Decreases in XRCC4 and DNA Lig3 and Lig4 are associated with a decline in NHEJ efficiency and fidelity, and impaired NEHJ has been reported after irradiation in previous studies using myeloma cell lines." (PMID 36420194, 2022).
non-small cell lung carcinoma (1 paper, 2023). A group of at least three distinct histological types of lung cancer, including non-small cell squamous cell carcinoma, adenocarcinoma, and large cell carcinoma. "A study among Chinese population showed that SNPs of XRCC4 were a risk factor for non-small-cell lung cancer carcinogenesis." (PMID 36765282, 2023).
Premature ovarian insufficiency (1 paper, 2024). Amenorrhea due to loss of ovarian function before the age of 40. "The loss of XRCC4 function resulted in impaired DNA repair in oocytes, which subsequently led to the development of premature ovarian insufficiency (POI)." (PMID 39023827, 2024).
prostate adenocarcinoma (1 paper, 2023). "However, XRCC4 was downregulated only in kidney chromophobe (KICH) and prostate adenocarcinoma (PRAD)." (PMID 36765282, 2023).
pulmonary embolism (1 paper, 2020). The obstruction of the pulmonary artery or one of its branches by an embolus, sometimes associated with infarction of the lung. "For the cardiac G×G, one SNP pair was identified through Biofilter modeling associated with venous thrombosis or pulmonary embolism: rs7735781 in XRCC4 and rs10804247 in XRCC5 (uncorrected LRT p = 3.20×10−6 and Bonferroni-adjusted LRT p = 0.0626996)." (PMID 32915819, 2020). "One SNP-SNP model in genes XRCC4 and XRCC5 was generated by Biofilter and identified as a significant interaction for venous thrombosis and/or pulmonary embolism." (PMID 32915819, 2020).
renal carcinoma (1 paper, 2023). A carcinoma arising from the epithelium of the renal parenchyma or the renal pelvis. "Moreover, the multiple organ tissue arrays obtained from HAP showed the protein expression of XRCC4 was upregulated in LIHC, BRCA, LUAD and Renal-cancer tissues." (PMID 36765282, 2023).
Testicular atrophy (1 paper, 2016). Wasting (atrophy) of the testicle (the male gonad) manifested by a decrease in size and potentially by a loss of fertility. "Nevertheless, p533KR/3KR XRCC4−/− mice display aging-like phenotypes including testicular atrophy, kyphosis, and premature death." (PMID 26943586, 2016).